ZDHHC1 (zDHHC palmitoyltransferase 1)
Diseases named in the same sentence as ZDHHC1 in open-access papers:
ZDHHC1 is named in the same sentence as 13 diseases in open-access papers, as found by Europe PMC text mining. Sharing a sentence is not in itself a finding about the gene and the disease. The quoted sentences say what the papers report.
adenosquamous carcinoma (1 paper, 2024). A carcinoma composed of malignant glandular cells and malignant squamous cells. "Human endometrial and adenosquamous carcinoma cells were transfected with a plasmid expressing the ZDHHC1 gene or control plasmid to generate ZDHHC1 overexpression or control lines." (PMID 38848146, 2024).
breast carcinoma (1 paper, 2021).
renal fibrosis (1 paper, 2023). A final common manifestation of a wide variety of chronic kidney diseases characterized by glomerulosclerosis and tubulointerstitial fibrosis. "However, the other PATs, such as ZDHHC6 (preferentially expressed in podocytes) and ZDHHC1, 2, 5 (up-regulated in the fibrotic kidneys), may also contribute to renal fibrosis by regulating palmitoylation of different substrates in various cell types." (PMID 37865665, 2023).
uterine corpus endometrial carcinoma (1 paper, 2024). A endometrial carcinoma (disease) that involves the body of uterus. "The zinc finger DHHC-type containing 1 (ZDHHC1) gene is implicated in the pathogenesis and progression of various malignant tumors, but its precise involvement in uterine corpus endometrial carcinoma (UCEC) remains unknown." (PMID 38848146, 2024). "Although the ZDHHC1 protein is implicated in the pathogenesis and progression of various cancers, its roles and mechanisms in uterine corpus endometrial carcinoma (UCEC) are unknown." (PMID 38848146, 2024).
tumor (17 papers, 2020 to 2025). "The ZDHHC1 gene is also implicated in tumor progression, with enhanced expression promoting cancer cell apoptosis, inhibiting cell cycle arrest and metastasis, and inducing oxidative and endoplasmic reticulum stress." (PMID 38848146, 2024). "A Cox regression analysis indicated that several factors, including clinical stage, age, histological subtype, residual tumor, tumor invasion, and ZDHHC1 expression, were associated with a reduced OS among patients with UCEC." (PMID 38848146, 2024). "Similarly, clinical stage, histological subtype, residual tumor, tumor invasion, and ZDHHC1 expression were significantly associated with a shorter DSS and PFI in the patients." (PMID 38848146, 2024). "Moreover, ZDHHC1, associated with pyroptosis, is a frequently silenced potential tumor suppressor by promoter methylation." (PMID 36589680, 2022). "ZDHHC1 has been identified as a potential tumor suppressor, with its expression frequently silenced in multiple tumor cells due to promoter methylation." (PMID 40814339, 2025). "Our study shows that ZDHHC1, acting as a tumor suppressor gene, inhibits the growth of CRC cells and downregulates the expression of LIPG through palmitoylation of IGF2BP1." (PMID 39069526, 2024). "Our study analyzed the correlation between tumor-infiltrating immune cells and ZDHHC1 expression in UCEC tissues and showed that ZDHHC1 expression significantly correlated with levels of various tumor-infiltrating immune cells and immune cell markers." (PMID 38848146, 2024). "To assess the importance of LIPG for the anti-tumor effects of ZDHHC1 in CRC, we used HCT116 and SW480 cells expressing shControl, shZDHHC1, shLIPG, and shZDHHC1/shLIPG." (PMID 39069526, 2024). "zDHHC1 was identified as potential tumor suppressor frequently silenced by epigenetic modifications like promoter methylation in cancer tissues and cell lines." (PMID 39429488, 2024). "Conversely, ZDHHC1 levels were significantly higher in individuals with high body weight (>80 kg), high body mass index (BMI) (>30), and tumor invasion (<50)." (PMID 38848146, 2024). "ZDHHC1 silencing increased tumor growth, and LIPG silencing alone inhibited the proliferation and invasion of CRC cells." (PMID 39069526, 2024). "Subsequently, zDHHC1 was identified as a tumor suppressor in cohorts of prostate cancer (PCa) patients." (PMID 39429488, 2024). "A study showed that the methylation level of the ZDHHC1 promoter was markedly increased in tumor tissue compared with neighboring normal tissue." (PMID 37394582, 2023). "On the cellular level, ZDHHC1 inhibited tumor cell growth by inducing apoptosis when ectopically expressed in multiple human cancer cell lines." (PMID 34282274, 2021). "We previously identified a hypermethylated gene ZDHHC1 that suppresses tumor growth when the expression was restored, but the specific mechanism was yet to be found." (PMID 34282274, 2021). "In our earlier work, we have identified Zinc Finger DHHC-Type Containing 1 (ZDHHC1) as a potential tumor suppressor that is hypermethylated in many cancers." (PMID 34282274, 2021). "Methylation-specific PCR (MSP) was conducted to examine the methylation status of ZDHHC1 promoter in an array of human tumor cells." (PMID 34282274, 2021).
tumor (continued). "In this study, we provided evidences showing ZDHHC1 as a potential tumor-suppressor is frequently silenced due to promoter methylation." (PMID 32863941, 2020). "To get more insights of the possible anti-tumor mechanisms of ZDHHC1, we used 8-plex isobaric tags for relative and absolute quantitation (iTRAQ) to identify altered pathways in MCF7 cells bearing stable ZDHHC1 transfection." (PMID 32863941, 2020). "All these results suggested that ZDHHC1 is frequently silenced in tumor through promoter methylation." (PMID 32863941, 2020). "Currently, we first reported that ZDHHC1 acts as a novel tumor suppressor, suppressing tumor cells' proliferation, stimulating apoptosis, and inhibiting cell migration and invasion." (PMID 32863941, 2020). "It was plain to see that cleaved caspase-3, 7 and PARP all upregulated in ZDHHC1 originated xenograft tumor in comparison of control group." (PMID 32863941, 2020). "All these factors showed decreased expression in ZDHHC1 overexpressing cells, indicating ZDHHC1 was capable of suppressing stemness of tumor cells." (PMID 32863941, 2020). "We next validated the tumor suppressing role of ZDHHC1 in vivo with a nude mice tumor xenograft model." (PMID 32863941, 2020). "Results showed a clear disparity where tumor derived from ZDHHC1 overexpressing cells manifested pronouncedly higher levels." (PMID 32863941, 2020). "ZDHHC1 also lowered the spheroid forming rate of cancer cells in spheroid forming assay, supporting that ZDHHC1 functions as a tumor suppressor that restrains EMT and cell stemness in human cancers." (PMID 32863941, 2020). "In CRC, ZDHHC1 acts as a tumor suppressor when at high levels." (PMID 39069526, 2024). "Correlation between ZDHHC1 overexpression and tumor-infiltrating immune cells." (PMID 38848146, 2024). "We found that ZDHHC1 knockdown profoundly induced tumor growth." (PMID 39069526, 2024). "A recent study revealed that the zinc finger DHHC-1 (ZDHHC1, also known as ZNF377) negatively regulated the tumor glucose metabolism pathway and pentose phosphate pathway (PPP), thereby playing a significant antitumor role, making it a potential new tumor suppressor." (PMID 37394582, 2023). "The suppression of ZDHHC1 through promoter methylation may increase oxidative and ER stress, promoting pyroptosis via the potential substrate NLRP3, thus implicating ZDHHC1 in tumor-suppressive mechanisms." (PMID 38067206, 2023). "ZDHHC1 exerted inhibitory effects on tumor migration, invasion, and proliferation." (PMID 36589680, 2022). "Moreover, it is highlighted necroptosis functions in apoptosis-resistant tumor cells as “fail-safe” insurance 29, providing a great reference value for us to test if conversion arisen by ZDHHC1 also includes necroptosis." (PMID 32863941, 2020). "Consistent with cell lines, tumor and adjacent normal tissues collected from representative carcinomas (colon, hepatocellular, nasopharyngeal, gastric, breast and lung tumors) were examined for ZDHHC1 promoter methylation with MSP and BGS." (PMID 32863941, 2020). "Together, ZDHHC1 is proved to also induce necroptosis, carving a propitious tumor cell demise mode." (PMID 32863941, 2020). "It remains to be determined if ZDHHC1 has palmitoyl-transferase activity and whether this activity is involved in its tumor suppression mechanisms." (PMID 32863941, 2020). "Therefore, we investigated if the tumor-suppressive effects of ZDHHC1 work through the CYGB-dependent glucose metabolism regulation pathway." (PMID 32863941, 2020). "ZDHHC1's salient anti-tumor abilities were recognized in vivo as well." (PMID 32863941, 2020).
tumor (continued). "Altogether, ZDHHC1 exerted the capacity to (i) suppress proliferation, (ii) induce apoptosis, and (iii) suppress migration and invasion, which is generally a critical feature of tumor suppressor gene in tumor cells." (PMID 32863941, 2020). "Collectively, these results confirmed that ZDHHC1 is able to suppress tumor growth in vivo." (PMID 32863941, 2020). "Moreover, ZDHHC1 overexpression was found lead to increased expression of epithelial markers like E-cadherin and Occludin, while reducing the expression of mesenchymal markers such as Vimentin and N-cadherin, indicating that ZDHHC1 acts as a tumor suppressor by inhibiting EMT in human cancers." (PMID 38233791, 2024). "However, these tumor suppressive effects may be attenuated by epigenetic modifications, such as tumor-suppression genes ZDHHC1 and DRD2." (PMID 34805183, 2021). "Furthermore, CYGB is essential for the function of ZDHHC1 as a tumor suppressor in cancer cells." (PMID 32863941, 2020). "Moreover, we focused succeeding works on whether transfected cells with siRNA-CYGB lose ZDHHC1's anti-tumor effects." (PMID 32863941, 2020). "Zinc Finger DHHC-Type Containing 1 (ZDHHC1, also known as ZNF377) belongs to the palmitoyl-transferase ZDHHC family, and is a potential tumor suppressor." (PMID 39069526, 2024). "Zinc finger DHHC-Type containing 1 (ZDHHC1), a recently discovered tumor suppressor gene, is silenced in a variety of cancers through abnormal hypermethylation to inhibit glucose metabolism and the pentose phosphate pathway." (PMID 35004688, 2021). "To determine the impact of ZDHHC1 knockdown on colorectal cell growth in vivo, we subcutaneously injected HCT116 cells (expressing shControl or shZDHHC1#2) into nude mice and assessed tumor growth." (PMID 39069526, 2024). "In conclusion, downregulated ZDHHC1 expression is associated with cancer cell growth, metastasis, poor prognosis, tumor immune infiltration, and RNA modifications in UCEC, emphasizing ZDHHC1 potential as a prognostic marker for the prognosis of patients with UCEC." (PMID 38848146, 2024). "Our study revealed that ZDHHC1 expression was significantly downregulated in UCEC and correlated with poor prognosis, cancer diagnosis, clinical stage, age, weight, body mass index, histological subtypes, residual tumor, tumor grade, and tumor invasion." (PMID 38848146, 2024). "In this article, we introduced a novel tumor suppressor gene (TSG), Zinc Finger DHHC-Type Containing 1 (ZDHHC1, also known as ZNF377), frequently silenced due to epigenetic modification among various cancers, which exerts significant anti-tumor effects through metabolic regulation." (PMID 32863941, 2020). "Conversely, above-normal ZDHHC1 expression inhibited the cell growth, cell cycle transition, migration, and invasion of UCEC cells, which may be related to the cell cycle, DNA replication, PI3K-AKT, and other pathways that promote tumor progression." (PMID 38848146, 2024). "The zinc finger DHHC-type containing 1 (ZDHHC1) protein correlates significantly with the occurrence and development of tumor and non-tumor diseases." (PMID 38848146, 2024).
cancer (11 papers, 2020 to 2025). A tumor composed of atypical neoplastic, often pleomorphic cells that invade other tissues. "In conclusion, considerably reduced ZDHHC1 expression in UCEC is associated with cancer cell growth, metastasis, poor prognosis, immune infiltration, and RNA modifications, revealing the promising potential of ZDHHC1 as a prognostic marker for UCEC." (PMID 38848146, 2024). "Based on the analysis of the six-gene signature, as an important predictor, ZDHHC1, which has been implicated previously in other cancers but rarely studied in PCa, was found to account for substantially high weight." (PMID 36589680, 2022). "Restoration of ZDHHC1 expression can inhibit cancer cell progression by stimulating apoptosis, inducing cell-cycle arrest, and repressing metastasis." (PMID 40814339, 2025). "Altered ZDHHC1 expression in UCEC was significantly associated with RNA modifications and the changes in cancer immune cell populations, such as CD56 bright NK cells, eosinophils, Th2 cells, and cell markers." (PMID 38848146, 2024). "Apart from ZDHHC1, the remaining five genes in the signature were also related to pyroptosis and cancer." (PMID 36589680, 2022). "Based on previous relevant studies, some reports suggest the role of ZDHHC1 in cancer, but for PCa, the evidence remains scarce." (PMID 36589680, 2022). "Our previous work suggested that ZDHHC1 was silenced or downregulated in many cancer cell lines and tissues due to promoter DNA hypermethylation." (PMID 34282274, 2021). "ZDHHC1 led to oxidative and ER stress, thereby stimulating pyroptosis and increasing cancer cell apoptosis." (PMID 32863941, 2020). "To investigate the role of ZDHHC1 in human cancer cells, we ectopically expressed ZDHHC1 in ZDHHC1-negative HONE1 and MCF7 cell lines by stable transfection." (PMID 32863941, 2020). "ZDHHC1 is ubiquitously expressed in normal adult and fetal tissues, but is silenced or downregulated in several cancer cell lines." (PMID 32863941, 2020). "Here, we determined that G6PD levels and ribose synthesis were significantly decreased in ZDHHC1 overexpressing cells, suggesting that ZDHHC1 inhibits cancer through the downregulation of G6PD-mediated glucose flux through the PPP." (PMID 32863941, 2020). "In summary, our experiments confirmed ZDHHC1 is downregulated in several cancer cell lines and multiple tumors by DNA methylation." (PMID 32863941, 2020). "The results furtherly suggested that ZDHHC1 inhibits glucose metabolism in cancer cells at least in part through the CYGB-mediated glucose metabolism pathway." (PMID 32863941, 2020). "We evidenced urgent oxidative stress in overloaded ZDHHC1 group, which appears beneficial in the cancer inhibition." (PMID 32863941, 2020). "Restoration of ZDHHC1 expression can curb cancer cell progression via stimulating apoptosis and cell cycle arrest, repressing metastasis, and reversing EMT transition and cell stemness." (PMID 32863941, 2020). "Additionally, transwell assays revealed that ZDHHC1 knockdown markedly impaired the invasion ability of cancer cells." (PMID 39069526, 2024).
cancer (continued). "Moreover, ZDHHC1 expression significantly correlates with cancer immune cells, cell markers, and RNA modifications, making ZDHHC1 a promising prognostic marker for UCEC." (PMID 38848146, 2024). "ZDHHC1 silencing significantly promoted cancer cell proliferation." (PMID 39069526, 2024). "The top DEGs upregulated in AA was endoplasmic reticulum-associated protein ZDHHC1, implicated in innate immune response and a positive regulator of the STING pathway, and ADAP1, which has been shown to promote cancer progression by inducing cell migration and invasion." (PMID 37732899, 2023). "We previously found that the ZDHHC1 promoter is hypermethylated in many cancers, causing the frequent lack of expression." (PMID 34282274, 2021). "The rescue experiment further verified that the knock-down of CYGB could partially reverse the ability of ZDHHC1 overexpression to inhibit the proliferation and induce apoptosis in cancer cell lines." (PMID 32863941, 2020). "We then investigated how ZDHHC1 suppresses cancer cell migration and invasion." (PMID 32863941, 2020). "We found ZDHHC1 is epigenetically silenced in a portion of cancer, and ectopic ZDHHC1 expression is able to diminish canonical cancer cell aggressiveness, most likely by reducing metabolic activity through promoting oxidative stress, ER stress mediated pyroptosis and apoptosis." (PMID 32863941, 2020). "Thus, it is likely CYGB is one of the key factors downstream of ZDHHC1 in suppressing glucose metabolism and thereby cancer cell growth." (PMID 32863941, 2020). "Therefore, targeting of ZDHHC1-mediated metabolic signaling pathways may be a promising strategy for cancer prevention and therapy." (PMID 32863941, 2020). "Our comprehensive analysis uncovered involvement of ZDHHC1 in the mechanisms allowing UCEC progression, including crucial signaling pathways that promote cancer progression." (PMID 38848146, 2024).
ZDHHC1 also shares sentences with these, for which no sentence is quoted: diabetes (2 papers); chronic kidney disease (1); colorectal cancer (1); Hypertension (1); inflammatory bowel disease (1); malaria (1); prostate carcinoma (1).